IL1B (interleukin 1 beta)
Diseases named in the same sentence as IL1B in open-access papers (continued):
Sharing a sentence is not in itself a finding about the gene and the disease.
joint disease (continued). "Starting at 8 years of age, F2:II-4 experienced the onset of a non-destructive, deforming arthropathy which has been refractory to broad-spectrum immunosuppression, anti-IL-1 receptor, anti-IL-1β and anti-TNFα therapies." (PMID 29259162, 2017). "On the other hand, indomethacin decreased IL-1β in the articular cavity as well as boiogito but failed to inhibit joint effusion in rats with OA." (PMID 26703073, 2015). "Although often considered a “non-inflammatory” joint disease, it is increasingly being recognized that cytokines, particularly IL-1β, and tumor necrosis factor-α (TNFα) may play an important role in both the progressive degradation of the cartilage and the disease symptoms." (PMID 23889808, 2013). "IL-1β and TNF are major mediators in various joint disorders, not only through their direct effects, but also via inducing the release and activation of other inflammatory mediators, being crucial in the initiation and/or perpetuation of an inflammatory insult." (PMID 31860662, 2019). "Finally, the bone and joint disease correction and lack of secondary storage-mediated amplification following TLR4 knock-out in MPS VII mice further proves the pivotal role of TNF-α in the periphery, as opposed to IL-1β." (PMID 35216110, 2022).
Still’s disease (35 papers, 2011 to 2025). "Both conditions frequently respond well to IL-1β/IL-1R1-blocking drugs, which argues for excessive/dysregulated IL-1β signaling to play a central role in Still’s disease pathology." (PMID 38231276, 2024). "At present, excessive IL-1β release from Still’s disease patients’ immune cells and elevated levels in serum or plasma remains hard to detect, using state-of-the-art detection platforms." (PMID 38231276, 2024). "IL-1β is a major cytokine in innate immunity, involved in the pathogenesis of various rheumatic diseases, notably systemic juvenile idiopathic arthritis (sJIA)." (PMID 38077384, 2023). "Canakinumab is a human monoclonal antibody targeting IL-1β which is used in the treatment of systemic juvenile idiopathic arthritis and active Still’s disease." (PMID 35207270, 2022). "The MoA models showed that in the autoinflammatory/systemic phases of Still’s disease, in which the innate immunity plays a pivotal role, the IL-1β-neutralizing antibody canakinumab is more efficient than the IL-6 receptor-inhibiting antibody tocilizumab." (PMID 33892792, 2021). "A similar decrease of IL-10 expression has been described in other auto-inflammatory diseases that are known to have increased IL-1β levels, such as systemic juvenile idiopathic arthritis." (PMID 33324407, 2020). "Treatment of IBD patients diagnosed with systemic onset juvenile idiopathic arthritis with IL-1β antagonists showed well-controlled systemic juvenile idiopathic arthritis (sJIA) symptoms at time of diagnosis of IBD." (PMID 31847438, 2019). "Rather, paw inflammation in Tnfaip3LysM-KO mice depended on IL-1β, suggestive of an autoinflammatory disease such as Still’s disease or juvenile idiopathic arthritis." (PMID 29515565, 2018). "While in systemic-onset juvenile arthritis (Still's disease) there is strong evidence supporting the role of innate immunity and IL-1β; in AOSD the most strong finding suggestive of NLRP3 and IL-1β involvement is the clinical improvement with IL-1β inhibitors." (PMID 23424598, 2013). "Chen and colleagues investigated the relationship between galectin-3 levels and disease activity in Still’s disease, an autoinflammatory disease, and reported that galectin-3 levels were elevated in these patients and positively correlated with IL-1β and IL-18 levels." (PMID 41008774, 2025). "Similarly, we also observed antibodies in Still’s disease plasma to disturb IL-1Ra function and facilitate unrestricted IL-1β signaling." (PMID 38231276, 2024). "An anti‐IL‐1β antibody has been approved by the FDA for the treatment of autoimmune disorders such as systemic juvenile idiopathic arthritis and adult‐onset Still's disease, and combining anti‐IL‐1β and anti‐PD‐1/L1 antibodies potentiates treatment effects in clinical applications." (PMID 37009412, 2023). "IL-1β may be selectively inhibited by canakinumab, a fully human monoclonal antibody which is actively used in rheumatologic disorders, such as systemic juvenile idiopathic arthritis and Still’s disease." (PMID 36555579, 2022). "Most importantly, the models provided feasible explanations of why IL-1β blockade may be an optimal therapeutic strategy for early-stage Still’s disease to prevent further disease progression." (PMID 33892792, 2021). "The pathophysiology of Still’s disease is largely unknown, but recent advances have identified interleukin (IL)-1β as a crucial inflammatory mediator." (PMID 31829244, 2019). "Therefore, therapeutics that block IL-1β and/or its biological functions have been approved to treat diseases such as RA, neonatal onset multisystem inflammatory diseases, and active systemic juvenile idiopathic arthritis." (PMID 28286780, 2017). "Furthermore, TNF-α immunomodulators have previously been used as a common treatment for RA and IL-1β immunomodulators are effective with other chronic diseases such as systemic-onset juvenile idiopathic arthritis and in adult onset Still's diseases." (PMID 21858242, 2011).
Still’s disease (continued). "Adult-onset Still’s disease (AOSD) and systemic juvenile idiopathic arthritis (sJIA) resemble a continuum of a rare, polygenic IL-1β-driven disease of unknown etiology." (PMID 38231276, 2024). "Canakinumab (ILARIS®), an IL-1 inhibitor, is a high-affinity, fully humanized monoclonal anti-IL-1β antibody approved for the treatment of CAPS, systemic juvenile idiopathic arthritis, and other periodic fever syndromes." (PMID 34959657, 2021). "Therefore, this study aimed to investigate whether the monoclonal IL-1β inhibitor canakinumab (CAN) shows differences in short- and long-term therapeutic outcomes according to the timing of its use in patients with Still’s disease in terms of different lines of biologic treatment." (PMID 38148914, 2023). "Interestingly, in patients with juvenile systemic idiopathic arthritis (SJIA), pulmonary involvement triggers a hyperinflammatory reaction and the appearance of secondary hemophagocytic lymphohistiocytosis (sHLH), as IFN, IL-1β, and IL-6 signature up-regulation can be observed." (PMID 34202243, 2021).
Zinc deficiency (34 papers, 2010 to 2025). A deficiency of the essential metal Zinc; an essential cofactor for many enzymes. "Zinc deficiency increases the proinflammatory cytokines’ production, such as IL-1β, IL-6, and TNF-α, as well as induces oxidative stress due to its scavenging properties against reactive oxygen species (ROS)." (PMID 41427149, 2025). "Previous studies explained the contribution of zinc deficiency to the increased risk of VOCs in SCD patients because zinc deficiency increases gene expression and production of interleukin 1β (IL-1β) and tumor necrosis factor α (TNF-α)." (PMID 40461893, 2025). "Zinc deficiency has been associated with elevated proinflammatory cytokine levels, particularly IL-1β, through the activation of inflammasome signaling pathways." (PMID 37892471, 2023). "Chronic zinc deficiency in a chick model triggered a decrease in gene expression of pro-inflammatory cytokines (IL-1β, IL-6, TNF)." (PMID 35344152, 2023). "According to previous studies, zinc acts as a crucial immune mediator against infection and inflammation, zinc deficiency enhances the generation of IL-1β and TNF-α in myeloid cells via epigenetic effects." (PMID 35602082, 2022). "Previously published studies underlined that zinc deficiency appears to promote the production of proinflammatory cytokines such as IL-1β, tumor necrosis factor alpha (TNFα), and IL-6 by myeloid cells and activated monocytes/macrophages." (PMID 34934131, 2021). "The zinc deficiency model shows that, even in mild deficiencies, IL-1β is produced by monocytes, and this suggests that zinc deficiency activates monocytes and macrophages in order to produce inflammatory cytokines and increase oxidative stress itself." (PMID 33255662, 2020). "The potential of zinc deficiency to skew the inflammatory reaction is supported by experiments in pro-myeolid (HL-60) cells, which increased production of IL-1B and TNFα after zinc depletion." (PMID 29731970, 2018). "Zinc deficiency increases the production of proinflammatory cytokines, such as interleukins IL-1β, IL-6, and tumor necrosis factor (TNF)-α." (PMID 28629136, 2017). "In our studies in the experimental model of zinc deficiency in humans, we showed that zinc deficiency per se increased the generation of IL-1β and its mRNA in human mononuclear cells following LPS stimulation." (PMID 25988117, 2014). "IL-1β is identified as an anchor of inflammation-cancer network in esophagus SCC in rats with zinc deficiency (ZD)." (PMID 25226614, 2014). "Zinc deficiency influences the generation of cytokines, including IL-1β, IL-2, IL-6, and TNF-α, and in response to zinc supplementation plasma cytokines exhibit a dose-dependent response." (PMID 22852057, 2012). "Similarly, in vitro studies have shown that Zinc deficiency results in increased IL‐6, IL‐1β production, and increased expression of intercellular adhesion molecule 1 that helps in leukocytes' extravasation." (PMID 36239436, 2022). "Zinc deficiency has a dose-dependent response to plasma cytokines, as zinc prevalence affects the production of cytokines, such as interleukins (IL-1β, IL-2, and IL-6) and tumor necrosis factor alpha (TNF-α) by MT homeostasis, which is, in turn, affected by proinflammatory cytokines." (PMID 33255662, 2020). "Moreover, zinc deficiency affects the incidence of inflammatory processes by influencing interleukin (IL)-1β production." (PMID 32183007, 2020). "Therefore, both CRP and serum albumin have been reported to be associated with elevated CRP, IL-6, TNF-α, IL-1β, and zinc deficiency." (PMID 30941358, 2019). "Zinc deficiency influences also production of interleukin (IL)-1β by macrophages." (PMID 26581375, 2016). "Altered production of cytokines during zinc deficiency may lead to inflammation, e.g., zinc depletion from macrophages induces IL-1β secretion and activates NLRP3 inflammasome." (PMID 26581375, 2016).
Zinc deficiency (continued). "However, IP-10 and IL-1b were up-regulated only in the ZnD/E group, suggesting an interaction between zinc deficiency and ethanol in cytokine expression." (PMID 24155903, 2013). "In our experimental human zinc deficiency model, even a mild deficiency increased ex vivo generation of IL-1β by monocytes, suggesting that zinc deficiency per se may activate monocytes and macrophages to generate inflammatory cytokines and increase oxidative stress." (PMID 25988117, 2014). "For example, zinc deficiency has been shown to increase the production of ROS and inflammatory cytokines (TNF-α, IL-1β, and IL-8)." (PMID 39683406, 2024). "Similar to our results, studies in both murine and human primary monocytes had shown zinc deficiency to impair TLR4-mediated signaling that resulted in reduced production of cytokines such as TNF-α, IL-6, IL-10, and Il-1β." (PMID 36558553, 2022). "Critically, we found that the combination of zinc deficiency and amyloidopathy is sufficient to induce NLRP3 activation and IL-1β release in mixed glia (and macrophages)." (PMID 33597269, 2021). "Zinc deficiency resulted in activating monocytes-macrophages, which resulted in increased generation of inflammatory cytokines such as TNF-α, IL-1β, and IL-6 and increased oxidative stress." (PMID 32411807, 2020). "Zinc deficiency over the long term reduces the integrity of lysosomes, activates the NLRP3 inflammasome, and induces IL-1β secretion in macrophages, while in the short term, zinc depletion by TPEN inhibits inflammatory activation." (PMID 30622979, 2018). "For example, zinc deficiency increases the levels of TNF-α, IL-1β, and IL-8 in a monocyte-macrophage cell line." (PMID 30622979, 2018). "We show here that depletion of zinc from macrophages, a paradigm for zinc deficiency, also activates the NLRP3 inflammasome and induces IL-1β secretion." (PMID 24481454, 2014). "The generation of a variety of cytokines, including IL-1β, IL-2, IL-6, and TNF-α, is reportedly influenced by mild to moderate zinc deficiency in humans." (PMID 22852057, 2012). "In the absence of malaria infection at the time of blood collection, zinc deficiency was associated with marginal reductions in concentrations of TNF, IL-1β and IL-10." (PMID 20470442, 2010). "Zinc deficiency promotes the production of IL-1β by increasing the accessibility of the IL-1β promoter, which possibly results in a constitutive IL-1β production even in the absence of danger signals." (PMID 40390089, 2025). "Zinc deficiency leads to the activation of monocytes/macrophages, which generate free radicals, causing oxidative stress and triggering the production of cytokines such as tumor necrosis factor (TNF-α), interleukin IL-1β, and IL-6." (PMID 38138191, 2023). "Zinc deficiency in humans activates monocytes-macrophages, which generate free radicals leading to oxidative stress and upregulate generation of inflammatory cytokines such as TNF-α, IL-1β, and IL-6." (PMID 32411807, 2020). "Zinc deficiency also augmented LPS-induced expression of IFNγ, CD80 and CD86 in murine macrophages either bone marrow-derived, or from cell culture, while expression of IL-1β, IL-6 and IL-10 was decreased." (PMID 29186856, 2017). "After PMA or LPS stimulation, human derived-promyelocytic leukemia (HL-60) and human vascular endothelial cells cultured in 1 μM zinc (zinc-deficiency) demonstrated significantly higher generation of TNF-α and IL-1β cytokines than cells cultured in 15 μM zinc (physiologic conditions)." (PMID 22852057, 2012). "In children with malarial infection, zinc deficiency was associated with increased production of IL-1β and IL-10, even if this increase did not bring the levels to those reached by individuals in the non-infected group." (PMID 20470442, 2010).
mood disorder (33 papers, 2016 to 2025). A cognitive disorder a disturbance in which the person's mood is hypothesized to be the main underlying feature. "Its expression is modulated by pro-inflammatory cytokines such as TNF-α and IL-1β, which are also implicated in mood disorders." (PMID 40491453, 2025). "It has been proposed that IL-1β, IL-6, and TNFα can directly modulate neuronal plasticity and cause mood disorders." (PMID 33402212, 2021). "Mood disorders associate with peripheral markers of low-grade inflammation, among which circulating levels of interleukin-1β (IL-1β) consistently predict diagnosis and poor outcomes." (PMID 34539454, 2021). "In the light of this association, we investigated the combined effect of IL-1β polymorphism and probiotic administration in mood disorder phenotypes." (PMID 32377159, 2020). "The aim of this study was to examine the combined effect of IL-1β polymorphism and probiotic administration in mood disorder phenotypes in the Italian population." (PMID 32377159, 2020). "TNF and IL-1β, like other pro-inflammatory cytokines, have been convincingly associated with mood disorders both in humans and rodents, and their levels increased in serum and CSF of MS patients, and in EAE brains." (PMID 27589957, 2016). "Furthermore, proinflammatory cytokine expression and circulating levels, like interferon gamma (INFγ), TNFα, IL-6, and IL-1β, are associated with mood disorder symptoms." (PMID 32377159, 2020). "The IL-1β expression is strongly influenced by some polymorphisms in the IL-1β gene, which increase the related cytokine levels, thus affecting the magnitude of inflammatory disorders, making them a determining cofactor in several chronic diseases and potentially in the onset mood disorders." (PMID 32377159, 2020). "LPS administration is known to elevate cytokine levels such as IL-1β, IL-6, and TNF-α, which contribute to neuroinflammation and are implicated in mood disorders." (PMID 40487411, 2025). "How the modulation of glycinergic currents by IL-1β in the CeA and other brain regions contributes to learning impairments and mood disorders is a matter of further investigation." (PMID 33746753, 2021). "Inflammatory cytokines can influence the onset and progression of several neurodegenerative mood disorders, and the IL-1β rs16944 SNP is related to high cytokine levels and potentially affects mood disorders." (PMID 32377159, 2020). "This process, also called “cytokine induced mood-disorder” can be induced by the systemic release of inflammatory cytokines including tumor necrosis factor alpha (TNFα), interleukin-6 (IL-6) and interleukin-1 beta (IL-1β)." (PMID 31734534, 2019). "Although IL-6 seems to be reliably activated by mental stress and to play an important role in mood disorders, other cytokines including TNF-α, IL-1ra and IL-1β appear to be relevant in the association of sedentary behaviour and mood but were not assessed in this study." (PMID 26294364, 2016). "Indeed, preclinical and clinical studies have repeatedly demonstrated that an increase in the expression and activation of this inflammasome induces a higher release of cytokines, such as TNF-α, IL-1β, and IL-6, which have been shown to be elevated in individuals with this mood disorder." (PMID 36613574, 2022). "Interleukin-1 beta (IL-1β) was clearly identified as an important player in the onset and progression of several neurodegenerative diseases, and numerous studies have already proved the link between mood disorder symptoms and proinflammatory cytokine expression and circulating levels." (PMID 32377159, 2020). "Then, IL-1β induces the secretion of CRH and the consecutive production of ACTH/glucocorticoids, resulting in mood disorders." (PMID 32076399, 2019). "Specific inflammatory markers such as TNF-α, IL-1β, CRP, and TSPO may be commonly involved in the pathogenesis of both SUD and mood disorders." (PMID 35558424, 2022).
mood disorder (continued). "IL-1β in turn induces the secretion of corticotropin-releasing hormone (CRH) and in consequence the secretion of adrenocorticotropic hormone (ACTH) and cortisol, which together with a plethora of further cytokines/chemokines lead to mood disorders." (PMID 32076399, 2019). "Due to this body of data it is reasonable to hypothesize that targeting P2X7, upstream of NLRP3 and IL-1β signaling, with CNS penetrable P2X7 antagonists would be beneficial for treating mood disorders." (PMID 29449810, 2018). "Levels of IL-1β were significantly higher in the group with mood disorder and anxiety disorder than in those without (p = 0.037 and p = 0.008, respectively)." (PMID 29631540, 2018). "Thus, the IL1B expression in the VAT was lower in obese patients with mood disorders than in those patients without mental disorders." (PMID 30504920, 2018). "Finally, the significant allelic ratio variation of SLA-DRB1 in the amygdala, combined with its known importance in regulating pro-inflammatory cytokines (e.g., IL-1β, IL-6, TNF-α) and microglial activation, supports its involvement in immune regulation and stress-related mood disorders." (PMID 40969342, 2025). "Furthermore, increased levels of PICs (i.e., IL-1β and TNFα) were also found in brain tissue after exposure to psychological stressors, an observation consistent with their role as potent activators of the HPA axis, which is commonly dysregulated in mood disorders." (PMID 26977323, 2016). "Studies have also shown that inflammatory markers may discriminate between treatment-resistant and non-resistant mood disorder patients, with the augmented levels TNF-α, IL-1β, and BDNF as markers of poorer antidepressant response." (PMID 35558424, 2022).